IL4 (interleukin 4)
Diseases named in the same sentence as IL4 in open-access papers (continued):
Sharing a sentence is not in itself a finding about the gene and the disease.
infection (continued). "Animals treated with mα-IL-25 showed a similar cytokine profile to non-treated mice, and in both groups, a type-2 response was generated with elevated gene expression of IL-4 and IL-13 after the challenge infection." (PMID 33276813, 2020). "To evaluate the impact of the infection in the pattern of cytokines in sera, we next performed ELISA tests of IL-4, IL-17A, IFN-γ, and TGF-β1 in patients and HC." (PMID 33281813, 2020). "On the thirtieth day after infection, a significant IL-4 mRNA downregulation was observed in C57BL/10 infected mice when compared with the control group." (PMID 32983013, 2020). "By contrast, the Th2 cytokine IL-4 promotes M2/alternatively activated macrophages, which express arginase-1 and shelter infection." (PMID 32477357, 2020). "On the contrary, prior infection with T. gondii attenuated IL-4 secretion when compare with S. japonicum group." (PMID 32295161, 2020). "The production of IL-4 is modulated by DENV during infection, which explains the crescent levels after the increase in viral particle administration or adjuvant-mediated inflammation." (PMID 32384822, 2020). "IL-4 is known as a regulatory cytokine that participates in control of the immune response against infection." (PMID 33604556, 2020). "In order to improve our knowledge of the interaction between the immune system and S. haemolyticus during the infection, we investigated the expression of IL1β, IL4, IL17, IFNγ, TNFα, TGFβ and IL10 by PBMCs infected withS." (PMID 32799619, 2020). "In the rat model of schistosomiasis, primary infection and secondary infection induce a Th2 cytokine response characterized by increased expression of IL-4, IL-5, and IL-13, which is driven by egg production in mice." (PMID 33013763, 2020). "The more heterologous antigens were secreted during infection, the more likely to trigger an IL-4-dominant response." (PMID 32381017, 2020). "We simplified the immune network by focusing on IL4 and IgA, and we were able to capture their fundamental signals and outcomes during the phases of detection, induction and expulsion of the infection process." (PMID 33226981, 2020). "Heightened concentrations of IL-6, TNFα, and IL-4 support previous pathogen exposure and a possibility of current infection." (PMID 32849592, 2020). "Following overexpression by GATA-3, the expression of IL-4/13A in the spleen was significantly higher (p < 0.05) on day 19 (day 4 post-infection) relative to the controls." (PMID 32326041, 2020). "IL-4 produced at sites of infection can induce Th2 lymphocyte differentiation and activate antibody production by B cells and inhibit the Th1 response; the Th2 response decreased bone loss in PD." (PMID 31978095, 2020). "The proportion of infection-elicited IFNγ+, IL4+ and polyfunctional CD4+ T-cells among influenza A/H1N1-infected patients were significantly greater than vaccine-elicited CD4+ T-cells against influenza A/H1N1 (p = 0.033, 0.026 and 0.042 respectively)." (PMID 32572168, 2020). "Laboratory mice experimentally infected with the gastrointestinal nematode Heligmosomoides polygyrus showed a decrease in levels of spleen IL‐4 after 21 days of infection, while MLN levels remain elevated up to 70 days after infection." (PMID 33391686, 2020). "IFN-γ and IL-4 production in the supernatant of frozen/thawed antigen stimulated splenocytes was assessed by passing eight weeks from infection." (PMID 31929528, 2020). "Further, type 2 innate lymphoid cell (ILC2) responses are at their most prominent in early infection, and IL-4/IL-13 from this subset is likely to contribute to the Th2 skewing observed in our model." (PMID 33117327, 2020). "In villous explants, the AgNp-Bio treatment downregulated production of IL-4, IL-6, and IL-8 after infection." (PMID 33552033, 2020). "The production of IL-4 during the initial phase of infection is sufficient to disrupt the Th1/Th2 balance towards a progressive disease in BALB/c mice, where Th2 cytokines are dominant." (PMID 33114674, 2020).
infection (continued). "The frequencies of splenic CD4+ T cells expressing IFN-γ, IL-10 and TNF-α were found similar in vaccinated and control mice, whereas a reduction of CD4+IL-4+ cells frequency was observed upon infection in vaccinated mice." (PMID 32040500, 2020). "In both single and dual infections the selected model indicates that specific IgA is stimulated by IL4 via a power law function." (PMID 33226981, 2020). "This suggests that early in infection M(IL‐4) macrophages contribute to a pathway leading to containment of mF later in infection." (PMID 32145033, 2020). "Susceptibility to L. major infection in WSX-1−/− mice is restricted to the initial stages of infection when a considerable level of IL-4 is produced." (PMID 32849534, 2020). "Surprisingly, however, the infection with Mtb per se promoted the LBs accumulation in M(IL-4) macrophages despite the activation of the IL-4/STAT6 axis." (PMID 33002063, 2020). "Granuloma formation around schistosome eggs is dependent on T cell-derived IL-4/IL-13 secretion and AAMs are critical to prevent a fatal infection in mice." (PMID 33042153, 2020). "After 4 weeks of infection, the host's immune response shifts to a Th2 type, producing cytokines such as IL-4, IL-10, and IL-13." (PMID 32373112, 2020). "This suggests that the variability in the levels of IL4 expression across individuals before infection is a major factor in determining the parasite load after infection." (PMID 31637219, 2019). "In contrast, experimental studies using gene-deficient mice in L. donovani infections have indicated that the control of not only primary infection, but also successful chemotherapy and successful vaccination is IL-4, IL-13, and IL-4Rα signaling-dependent." (PMID 31475014, 2019). "In contrast, PCLS from HDM-sensitized mice showed an attenuated antiviral response, but exaggerated IL-4, IL-6, and IL-10 secretion upon infection." (PMID 31640701, 2019). "In contrast, LCMV cl13 infection of IL-4-/- recipients resulted in an overall decrease of specific CD8+TE immunity, including a 4.0-fold reduction of the splenic Io CD8+TE response (p = 0.0056)." (PMID 31697793, 2019). "In summary, the major fluctuations in cytokine/chemokine dynamics relevant to the observed changes in immune cells after NTHi infection of the Junbo mouse middle ear were for IL-12p40/p70, IL-4, and TGF-β." (PMID 31548315, 2019). "At day 2 of NTHi infection, the level of the major Th2-dependent cytokine, IL-4, was significantly increased and then remained high in the later days of NTHi infection." (PMID 31548315, 2019). "IL-4, which is produced by basophils was elevated above baseline beginning around 6 days post-infection in the surviving animal, and peaked at day 14, similar to the peak population of basophils in this animal." (PMID 31166946, 2019). "At day 2 of NTHi infection, the IL-4 levels significantly increased above the base value for middle ear fluid in the noninoculated Junbo mouse." (PMID 31548315, 2019). "They observed inhibition of some of the most critical cytokines for parasite growth and the establishment of infection, including granulocyte-macrophage colony-stimulating factor, interleukin-4 (IL-4), IL-10, and tumor necrosis factor (TNF)." (PMID 30881596, 2019). "Specifically, expression significantly increased in PFOS/GaHV-2 cells compared to PFOS only, for NF-κB (p = 0.002), IL-8 (p = 0.013) and IL-4 (p < 0.001) at 24 h post-infection." (PMID 31238913, 2019). "In murine PCM, PGE2 had an immunosuppressive effect at early steps of infection, by a mechanism dependent on IL-10 and IL-4." (PMID 31886295, 2019). "Analysis of anti-inflammatory cytokines revealed a peak of IL-4 and IL-5 in cerebra of T. canis-infected mice in the subacute phase of infection, decreasing to homeostatic conditions as of day 42 pi." (PMID 31315623, 2019).
infection (continued). "To examine the involvement of c-Maf, Bach-1, and Elmo-1 in Mtb-growth promotion within M(IL-4/IL-13) BMDMs, we knocked-down these target genes using GapmeRs in M(IL-4/IL-13) BMDMs prior to infection with Mtb." (PMID 30941122, 2019). "After infection, the level of IL-4 in the immunized group was at a similar value than before infection, but the level of IL-10 was clearly lower than before infection." (PMID 31681308, 2019). "Beijing-1585 and EAI-1627 infection elicited significant IL-4 protein levels in the lungs, thus matching the observed increase in B-cells." (PMID 31882653, 2019). "Specifically, in pregnant sheep, the level of IL4 mRNA after infection with N. caninum, was the same at the first and third terms of gestation." (PMID 31533826, 2019). "While IL10 increased after infection at the last term of gestation, IL4 showed higher levels on the first and second term." (PMID 31533826, 2019). "For instance, in the RV144 trial, CD4+ T-cells secreting IL-2, TNF-α, IFN-γ, IL-4, and CD154 in response to HIV-1 envelope peptides were associated with lower infection rates in vaccine recipients." (PMID 31382453, 2019). "A general upregulation of the immune response was found when comparing dual with single infection, specifically, of the significant variables 71% were upregulated such as IL4, IL5, IFNγ, and IL10." (PMID 31871660, 2019). "In single infections with T. retortaeformis, there was a general upregulation in the post‐ relative to the pretreatment phase, notably for IL4, IL10 and TGFβ." (PMID 31871660, 2019). "Compared with infections with low-uptake strains that secreted higher IL-17, infection with high-uptake C. neoformans strains induced higher secretions of bronchoalveolar lavage IL-4 and IL-13, the major cytokine profiles of type-2 immune responses." (PMID 30520685, 2019). "In contrast, the levels of IL-4 and IL-10 cytokines were diminished at 14 weeks post-infection in the HisAK70-immunized animals." (PMID 31739549, 2019). "It proved that the increase of IL-4 is an indicator in favor of the host at the late stage of infection." (PMID 30642401, 2019). "The splenic infection of L. donovani causes a constitutive expression of chemokine ligand 2 (CCL2) or monocyte chemoattractant protein 1 (MCP-1), which triggers IL-4 secretion from Th2 cells that activates the MΦs in alternative manner." (PMID 31024534, 2019). "Following amplification, an increased frequency of CD4+ iNKT cells producing IL-4 was noticed in the group of patients free of infection compared with those who became infected and with healthy donors." (PMID 31253189, 2019). "Abundance was negatively associated with type 2 (IL4, IL5, single and dual infections) and regulatory T cells (FoxP3, single infection), and positively related to the inflammatory response (Tbet, RORγT, dual and single infections)." (PMID 31871660, 2019). "Compared with the 30 h infection group, the expression of IL-4 in the infected group was significantly increased at 6 dpi." (PMID 31855175, 2019). "The two anti-inflammatory cytokine IL-10 and IL-4 were also produced less after infection, suggesting an overall reduction in the cytokine response during infection in AIC." (PMID 31801841, 2019). "Of particular relevance to the current study, IL-4 contributes to increased antibody responses after infection." (PMID 30665337, 2019). "We reasoned that infection mediated by TIM-4 obscured the subtler effects of IL-4/IL-13 treatment and the effect of IL-4/IL-13 would likely be more profound in TIM-4-null pmacs." (PMID 31825972, 2019). "Instead, experiments on in vitro mucosal surfaces showed that the local cytokine environment, namely IL-4, and infection have major effects on mucin production and transport speed." (PMID 30665337, 2019). "Corresponding to this finding, infection with high-uptake C. neoformans resulted in enhanced arginase enzyme activity, elevated IL-4 and IL-13 and lowered IL-17 in the bronchoalveolar lavage." (PMID 30520685, 2019).
infection (continued). "IL-10 and IL-4 are important negative regulators of inflammatory responses during the course of infection with T. gondii, which are sufficient to provoke a Th1 immune response to avoid host mortality associated with the development of severe immunopathology." (PMID 31456786, 2019). "In Norway rats, the concentrations of IFN-γ and IL-4 were increased and peaked on days 10 to 20 after inoculation with Seoul virus suggesting that both Th1 and Th2 responses are facilitated following infection." (PMID 31008105, 2019). "Here we show that IL-4/IL-13 polarization of murine peritoneal macrophages enhances EBOV GP-dependent infection by increasing cell surface expression of CLRs." (PMID 31825972, 2019). "Other cytokines like IL-12, MCP-1, IL-10, IFN-γ, and IL-4 have also been shown to mediate either pro-inflammatory or anti-inflammatory activities during infection." (PMID 31824512, 2019). "It has been reported that serum cytokines such as IL-4 and IL-15 were significantly elevated in patients with severe infection." (PMID 30787914, 2019). "The switch from classically activated to alternatively activated macrophages later during infection by type II cytokines such as IL-4, IL13, and TSLP is critical for maintaining a Th2 type environment which have anti-inflammatory properties." (PMID 31824512, 2019). "Two cell populations determine leishmanial condition: Th1 (IFN-γ, IL-2) in the protective condition and Th2 (IL-4, IL-10, and IL-13) in progressive infection." (PMID 30834079, 2019). "Among the tested proinflammatory and anti-inflammatory cytokines, there were significant differences in the mRNA expression levels of IL-2, IL-4, IL-6, and IL-10 following infection with the virulent vs. the attenuated strain (p < 0.05)." (PMID 31514454, 2019). "In contrast, if macrophages are eliminated at an early stage of infection, a permissive Th2-type response is established with a high production of IL-4 and a low production of IFN-γ, which favors the parasite growth." (PMID 30538171, 2019). "In conclusion, incubation with IL-4 let C3H/He and BALB/c macrophages more susceptible to infection, but the difference in susceptibility was unaltered." (PMID 31856207, 2019). "Our previous studies also documented a biphasic curve of IL-4 mRNA expression, with a very early peak at 2 to 8 days after intrahepatic infection, which was also found in the present study." (PMID 30037796, 2018). "The spatiotemporally restricted production of IL-4 by NKT cells appears to instruct antigen-activated B cells at the periphery of B cell follicles early after infection for the subsequent seeding of germinal centers." (PMID 29249358, 2018). "Our analysis of naturally infected calves shows an association with increased eosinophil counts, IL-4 production, and IL-5 transcription and decreased IFN-γ production, indicating polarization toward a type 2 response as infection progresses." (PMID 28993458, 2018). "It is worth mentioning here that the mammalian key type 2 cytokine, IL-4, has been shown in the avian immune system to be less expressed compared to IL-13 in several extracellular infection models, hence measuring IL-13 was opted in the current study." (PMID 29892298, 2018). "This matches the increase of serum antibody levels observed post-infection and the significant positive relations between IL-4, IL-10 and antibody titers shown in this study, indicating a Th2-biased immune response." (PMID 29973271, 2018). "Th2 cytokines, il4/13a and il4/13b2, were significantly up-regulated from 2 days post-infection onwards, and changes were lesion-specific." (PMID 30209326, 2018). "At all-time points measured following infection, the concentrations of IL-4 and IL-17 in cell culture supernatants were not significantly different between BCG+ and BCG- groups." (PMID 30204787, 2018).
infection (continued). "There were no significant changes in the secretion of the type II cytokine IL-4, but type II cytokine IL-5 was increased post-infection; the RH group had lower IL-5 levels than the ME49 group at day 5 and 9 post-infection." (PMID 30564216, 2018). "At 8-weeks post-infection ferrets displayed a mixed Th1/Th2 cytokine profile, with increased transcription of both IFNγ and IL-4." (PMID 29601572, 2018). "It has been reported that inflammatory cytokines, including TNF-α, IL-4, and IL-13, promote mucin gene expression in intestinal epithelial cells and prevent pathogen infection and colonization." (PMID 29867964, 2018). "Regarding the Th2 cytokine profile, IL-4 expression was apparently increased because of infection in both groups, but this upregulation was statistically significant only in infected/non-pregnant MIF-/- females (P < 0.05)." (PMID 29867817, 2018). "Th2 response was highest in response to N40 infection followed by that in B. microti infected old mice; however, IL-4 production only occurred after in vitro stimulation." (PMID 30619263, 2018). "Compared with unimmunized control mice, the expression of IL‐4 and IL‐17 primed by DCs from the 4‐week post‐infection group increased when accompanied by NP30 immunization." (PMID 29577333, 2018). "In line with the clinical findings, C57BL/6 IFN-β−/−, IFNAR1−/−, and WT mice exhibited similar mRNA expression levels of IFN-γ, interleukin (IL)-4, IL-12, IL-13, inducible nitric oxide synthase, and arginase 1 during the acute and late phase of the infection." (PMID 29459858, 2018). "Plasma levels of TNF-α, IFN-γ, IL-6, IL-10, CXCL10, CCL2 and IL-4 were all increased upon infection." (PMID 30375380, 2018). "These authors mention that, in addition to the production of these cytokines and the increased production of IL-4, a suppressive immune response was also induced in patients infected with E. histolytica, which, in turn, favored a symptomatic infection." (PMID 30406037, 2018). "Analyzing mRNA for components of L-arginine metabolism, we observed that the effect of IL-4 on infection progression was via the increase of Arg1 and Larg mRNAs, while the effect of IL-13 on infection progression was only via the increase in Larg mRNA." (PMID 30150896, 2018). "This study is aimed at evaluating IL-4 role in immune response modulation of mice infected with T. cruzi Colombian strain in acute phase of infection." (PMID 30622430, 2018). "The increase in immune cytokines (IL-12p70, IL-4, IL-5, and IL-17A) induced by SPY1 were further upregulated by P17 treatment, whereas the decrease in the infection-associated inflammatory cytokine TNF-α by SPY1 was reversed." (PMID 30116243, 2018). "Nonetheless, in white blood cells, IL-4, IL-6 and IL-10 mRNA-levels significantly increased after infection, whereas IFN-ɣ, IL-2 and TGF-β expression tended to decrease." (PMID 29973271, 2018). "The IL‐4 and IL‐5 expression levels from the NP30‐immunized mice were higher than those from the control group, and IL‐4 levels were also higher in the 4‐week post‐infection group." (PMID 29577333, 2018). "Mice deficient in NO-synthesis by iNOS, especially in the context of infection, were shown to exhibit an enhanced Th1 response with higher IFNγ and less IL4 secretion." (PMID 30030528, 2018). "In immunized mice, increase in immune cytokines (IL-12p70, IL-4, IL-5, and IL-17A) induced by SPY1 were further upregulated by P17 treatment, whereas the decrease in the infection-associated inflammatory cytokine TNF-α by SPY1 was reversed." (PMID 30116243, 2018). "Studies on experimental and natural human infections with hookworms have observed that the infection triggers strong Th2 cytokines (especially IL-4, IL-5, IL-9 and IL-13), regulatory IL-10 and TGF-β1 responses." (PMID 30274434, 2018).